FRAS1 (Fraser extracellular matrix complex subunit 1)
Diseases named in the same sentence as FRAS1 in open-access papers (continued):
Sharing a sentence is not in itself a finding about the gene and the disease.
tumor (11 papers, 2018 to 2025). "The circ102049 levels in tumor tissues were positively associated with the FRAS1 mRNA expressions but negatively associated with the mature miR‐761 or miR‐192‐3p levels." (PMID 33131207, 2021). "This may partially explain the differential mRNA expression of FRAS1/FREM between tumor tissues and normal tissues, while the somatic mutation rates of them in KIRC were low." (PMID 36249757, 2022). "Recent studies show that FRAS1 was associated with tumor metastasis." (PMID 36008805, 2022). "The novel tuft cell ligands encoded by Frem1, Fras1 and Agt may have tumor suppressor functions, but have also been found to correlate with immune infiltration and metastasis, while Mif could suppress anti-tumor immunity of infiltrating immune cells." (PMID 37386128, 2023). "The results revealed that, except for LINC00665 and FRAS1, all the other 10 mRNAs exhibited significantly higher expression in tumor samples than in normal samples (p < 0.001)." (PMID 35233461, 2022). "The excessive tumor growth induced by METTL3 upregulation was blocked by FRAS1 or YTHDF1 knockdown, including tumor volume and tumor weight." (PMID 36008805, 2022). "Decreased FRAS1/FREM expression levels were significantly associated with advanced clinicopathological parameters (pathological stage, grade and tumor metastasis status)." (PMID 36249757, 2022). "Consistent with the public database analysis, FRAS1 mRNA level was decreased in tumor tissues compared to normal tissues." (PMID 36008805, 2022). "In this study, METTL3/YTHDF1 elevated FRAS1 protein expression, thus accelerating cell proliferation and tumor growth (colony formation)." (PMID 36008805, 2022). "The low expression level of FRAS1 gene was significantly correlated with advanced clinical stage (p = 7.1E-10), high pathological grade (p = 1.2E-10) and tumor metastasis status (p = 0.016)." (PMID 36249757, 2022). "We would collected more samples to identify the expression of FRAS1 mRNA level between tumor tissues and normal tissues." (PMID 36008805, 2022). "To confirm the role of METTL3/FRAS1 axis in vivo, we verified its effects on tumor growth using xenograft tumor model." (PMID 36008805, 2022). "In recent years, an increasing number of studies have identified FRAS1 that play crucial roles in tumor carcinogenesis." (PMID 33131207, 2021). "In sunitinib resistant tumor cells, miR-663 targets FRAS1 (Fraser Extracellular Matrix Complex Subunit 1) and MDGA1 (MAM Domain Containing Glycosylphosphatidylinositol Anchor 1) transcripts." (PMID 29987196, 2018). "Taken together, METTL3-induced FRAS1 promotes NSCLC tumor growth in vivo." (PMID 36008805, 2022). "To explore whether FRAS1, FREM1 and FREM2 were involved in the process of immune infiltration in KIRC, we employed TIMER 2.0 to exhibit the landscape of FRAS1/FREM correlating with tumor purity and various immune infiltrates in human cancers." (PMID 36249757, 2022). "However, the m6a level and the protein level of FRAS1 was significantly increased in 3 cases of tumor tissues compared to the paired corresponding normal tissues." (PMID 36008805, 2022). "Notably, we used datasets GSE105261 (9 primary KIRC vs. 26 matestasis of KIRC) and GSE22541 (24 primary KIRC vs. 24 matestasis of KIRC) from GEO database to study whether FRAS1/FREM could be tumor metastasis markers." (PMID 36249757, 2022). "However, interestingly, circ102049 significantly promoted the liver metastasis of CRC cells, whereas silencing FRAS1 could weaken the metastatic capacity of tumor cells." (PMID 33131207, 2021). "Both FRAS1 and CDON are involved in tumor progression, promoting tumor cell proliferation and colony formation." (PMID 38202722, 2023). "The most enriched glycoproteins in tumour ECM compared to non-tumour ECM included thrombospondin-2 (16.9-fold), MXRA5 (14.4-fold), peroxidasin (2.5-fold), thrombospondin-1 (2.5-fold), SPARC (2.3-fold), FRAS1 (2.3-fold) and tenascin-C (2.1-fold)." (PMID 37397358, 2023).
tumor (continued). "In summary, our first pan-cancer analyses indicated that the FRAS1/FREM genes and proteins were differentially expressed between tumor and normal tissues." (PMID 36249757, 2022). "The expression levels of FRAS1, FREM1 and FREM2 in both KIRC and non-tumor tissues were also measured by qRT-PCR verification, which confirmed the expression profiles of FRAS1/FREM family." (PMID 36249757, 2022). "A better understanding of the interplay between FRAS1/FREM and the tumor microenvironment might be the key to unlock a new era of oncological treatments and proposes new therapeutic targets for KIRC." (PMID 36249757, 2022). "The difference in expression of FRAS1 RNA level between tumor and normal tissues was not accurately reflected." (PMID 36008805, 2022). "Besides, FRAS1, FREM1 and FREM2 mRNA and protein expressions were correlated with the clinicopathological characteristics (pathological stage, grade and tumor metastasis status) of the patients with KIRC." (PMID 36249757, 2022). "FRAS1 silence or YTHDF1 silence could rescue the elevated NSCLC cell proliferation, colony formation, and tumor growth induced by METTL3 overexpression in vitro and in vivo." (PMID 36008805, 2022). "As expected in vitro, neither circ102049 or FRAS1 promoted tumor growth, and no rescued effects of si‐FRAS1 were observed in circ102049‐overexpressed mice." (PMID 33131207, 2021). "YTHDF1 has been identified to be critical for NSCLC proliferation In this study, we found that YTHDF1 was highly expressed in NSCLC tumor tissues compared to normal tissues via UALCAN, indicating that YTHDF1 may play a critical role in m6A-regulated FRAS1 expression." (PMID 36008805, 2022). "Interestingly, FRAS1 and FREM2 expression decreased in the stage I and stage II patients who had a high propensity to metastasise, which means FRAS1 and FREM2 could be tumor metastasis markers of KIRC." (PMID 36249757, 2022).
cancer (8 papers, 2018 to 2023). A tumor composed of atypical neoplastic, often pleomorphic cells that invade other tissues. "For instance, increased expression of COL6A1, SDC4, FRAS1, AGRN, and COL4A2 has been observed in different cancer types and reported to be associated with metastasis and poor outcomes in patients." (PMID 37987316, 2023). "The regulatory network of “writer” METTL3, “reader” YTHDF1, and “target” FRAS1 inspires the understanding of m6A-dependent gene regulatory mechanism in cancer biology, which offers a possibility of m6A regulators as promising biomarkers in NSCLC." (PMID 36008805, 2022). "It was observed that CDON, YTHDF1 and METTL3 were highly expressed in cancer tissues compared to that of in corresponding normal tissues, suggesting that there was a positive relationship between FRAS1, CDON, and METTL3/YTHDF1." (PMID 36008805, 2022). "FRAS1/FREM are also found to be involved in the progression of several cancers, such as lung cancer, gastric cancer, breast carcinoma and isocitrate dehydrogenase (IDH)- wild-type glioblastoma." (PMID 36249757, 2022). "MDGA1, FRAS1 or the targeting miRNAs can be potential adjuvant therapeutic targets, through inhibition of cancer cell migration, thus eliminating the development of resistance and metastasis." (PMID 29435133, 2018). "FRAS1/FREM family are involved in the progression of several cancers." (PMID 36249757, 2022). "It will be interesting to investigate whether FRAS1/FREM might serve as new targets for the development of various cancer immunotherapies." (PMID 36249757, 2022). "The mRNA expression levels of FRAS1, FREM1 and FREM2 were analyzed in Oncomine over a cancer-wide range." (PMID 36249757, 2022). "Our study explored the relationship between FRAS1, FREM1 and FREM2 promoter methylation and cancer for the first time." (PMID 36249757, 2022). "For CSS, patients with cancer-specific death presented higher expression patterns of RGPD8, BAIAP2L1, and DDX11 and lower expression patterns of SLC16A9, FRAS1, AQP1, TMEM38B, and PRUNE2, in both the univariate and multivariate analyses." (PMID 31963294, 2020). "However, other genes of the same gene family as FREM2, namely FRAS1 and FREM1, were recently reported as cancer-related genes." (PMID 34439271, 2021). "Indeed, two other genes in the FRAS/FREM family, FRAS1 and FREM2, have been shown to be related with the occurrence and progression of certain carcinomas." (PMID 33058542, 2020).
genetic diseases (2 papers, 2021 to 2024). "This is consistent with the fact that individuals with HNF1B mutations do have kidneys, in contrast to certain other human genetic diseases (e.g., FRAS1 or FREM2 mutations) where organogenesis fails to initiate." (PMID 38788724, 2024).
neurological disease (1 paper, 2017). "Four of these genes have already been implicated in a neurological disease (TMEM67, FGFR1, FRAS1 and EXOSC8), but most variants affect genes that have not previously been connected to human disease phenotypes." (PMID 27457812, 2017).
skeletal dysplasia (1 paper, 2013). Any Mendelian diseases that affects growth and development of the skeleton. "Detailed analysis of Fras1bfb/bfb skeletons does not reveal any overt skeletal dysplasia, similar to previously characterised Fras1 mutants." (PMID 24143185, 2013).
FRAS1 also shares sentences with these, for which no sentence is quoted: cryptophthalmos (4 papers); Manitoba oculotrichoanal syndrome (3); endometrial carcinoma (2); ablepharon macrostomia syndrome (1); bifid nose (1); Blepharocheilodontic syndrome 2 (1); Branchio-oculo-facial syndrome (1); connective tissue disorder (1); dysplasia (1); Ellis-van Creveld syndrome (1); end-stage renal disease (1); Epileptic encephalopathy (1); heart malformations (1); infection (1); Junctional epidermolysis bullosa gravis of Herlitz (1); kidney cancer (1); Mayer-Rokitansky-Küster-Hauser syndrome (1); melanoma (1); mental retardation (1); multiple myeloma (1); Noonan syndrome (1); orofacial cleft (1); osteogenesis imperfecta (1); ovarian carcinoma (1); prostate carcinoma (1); renal clear cell carcinoma (1); syndactyly (1); thyroid cancer (1).